EDEM3 (ER degradation enhancing alpha-mannosidase like protein 3)
Description:
Involved in endoplasmic reticulum-associated degradation (ERAD). Accelerates the glycoprotein ERAD by proteasomes, by catalyzing mannose trimming from Man8GlcNAc2 to Man7GlcNAc2 in the N-glycans. May also participate in mannose trimming from all glycoproteins and not just misfolded ones targeted to ERAD. May have alpha 1,2-mannosidase activity (By similarity).
Synonyms: C1orf22; CDG2V
Tractability: Antibody: UniProt predicts a signal peptide or a membrane-spanning region. PROTAC: ubiquitination databases record sites on it; its protein half-life has been measured.
Gene: Protein-coding gene on chromosome 1 (184,690,237 to 184,754,907, reverse strand). Ensembl gene ENSG00000116406.
Subcellular location: Endoplasmic reticulum lumen
Subcellular location (Human Protein Atlas): Endoplasmic reticulum
Pathways (Reactome):
Metabolism of proteins: ER Quality Control Compartment (ERQC)
Gene Ontology:
Molecular function: mannosyl-oligosaccharide 1,2-alpha-mannosidase activity; calcium ion binding
Biological process: endoplasmic reticulum mannose trimming; ERAD pathway; endoplasmic reticulum unfolded protein response; mannose trimming involved in glycoprotein ERAD pathway; ubiquitin-dependent glycoprotein ERAD pathway; carbohydrate metabolic process; glycoprotein catabolic process
Cellular component: endoplasmic reticulum quality control compartment; endoplasmic reticulum; endoplasmic reticulum lumen; membrane
Genetic constraint (gnomAD): Loss-of-function variants: 43 observed, 82.6 expected, observed/expected ratio (o/e) 0.52, 90% interval 0.41 to 0.67. The upper end of that interval is the gene's LOEUF score, 0.67, which puts it in group 2 of 6, group 1 being the genes least tolerant of losing a copy. Missense variants: 831 observed, 954.74 expected, observed/expected ratio (o/e) 0.87, 90% interval 0.82 to 0.92. Synonymous variants: 290 observed, 329.4 expected, observed/expected ratio (o/e) 0.88, 90% interval 0.8 to 0.97.
Gene-disease validity (ClinGen):
ClinGen rates the evidence that EDEM3 causes each of these diseases.
congenital disorder of glycosylation, type 2v (autosomal recessive): Strong.
Homologues: Orthologues: chimpanzee EDEM3 (99% identical), macaque EDEM3 (99% identical), dog EDEM3 (97% identical), pig EDEM3 (96% identical), mouse Edem3 (94% identical), rat Edem3 (93% identical), guinea pig EDEM3 (85% identical), rabbit EDEM3 (83% identical), tropical clawed frog edem3 (78% identical), zebrafish edem3 (67% identical), Caenorhabditis elegans ZC506.1 (43% identical), Drosophila melanogaster Edem2 (42% identical), and 3 more. Paralogues in human: EDEM1 (25% identical), EDEM2 (24% identical), MAN1A1 (17% identical), MAN1C1 (16% identical), MAN1A2 (16% identical), MAN1B1 (16% identical).